BRCA2 (BRCA2 DNA repair associated)
Diseases named in the same sentence as BRCA2 in open-access papers (continued):
Sharing a sentence is not in itself a finding about the gene and the disease.
tumor (continued). "Initially, the patient was counseled that she had pathogenic constitutional alterations of BRCA2 and MLH1, based on tumor and constitutional sequencing results." (PMID 25712765, 2015). "Reduced BRCA2 expression disrupts homologous DNA recombination repair mechanisms, leading to tumor formation." (PMID 26202431, 2015). "Among these, BRCA1 and BRCA2 tumours are phenotypically most different and we consider these two for our analysis here; our dataset contains 19 BRCA1 and 30 BRCA2 expression samples (GEO accession GSE19177)." (PMID 25521701, 2014). "Interruption of BRCA1 and BRCA2 expression or their function is also found to enhance radiosensitivity and the chemotherapeutic effectiveness of tumor cells." (PMID 25337721, 2014). "Future studies of additional BRCA1 and BRCA2 carriers with detailed tumor pathology information on new and previously recruited mutation carriers are needed." (PMID 25919761, 2014). "One of the reasons that this was obscured in univariate analysis is that the BRCA1-likeCGH tumors ended up in the non- BRCA2-likeCGH tumor group, thereby confounding the analysis." (PMID 24887359, 2014). "BRCA1 tumours displayed higher co-expression compared to BRCA2 tumours, ∼15700 PPIs with higher correlations." (PMID 25521701, 2014). "In the case of BRCA1 vs BRCA2 tumours, only four of the influential TFs (GATA3, ESR1, FOXA1 and XBP1) were identified as differentially expressed." (PMID 25521701, 2014). "While most complexes showed a decrease in co-expression from normal to PDAC (159 out of 256) and from BRCA1 to BRCA2 tumours (225 out of 277), interestingly a considerable number of complexes showed an increase (96 and 52)." (PMID 25521701, 2014). "Top enriched terms in KEGG pathways and Biological Process in disrupted complexes in pancreatic (normal vs PDAC) and breast (BRCA1 vs BRCA2) tumours (using DAVID)." (PMID 25521701, 2014). "BRCA1 tumours, being predominantly basal-like, do not express ER and therefore show lower expression of ER targets compared to BRCA2 tumours, which are predominantly luminal-like and express ER." (PMID 25521701, 2014). "A similar analysis in BRCA1 vs BRCA2 tumours highlighted increase in PPI co-expression around the mitotic regulators CDK1, CDC20 and CKS1B and the histone deacetylases HDAC1 and HDAC6; these are known drug targets for which inhibitors have been developed." (PMID 25521701, 2014). "Overall, we noticed considerable drop in co-expression for PDAC vis-a-vis normal, whereas BRCA1 tumours showed higher co-expression vis-a-vis BRCA2 tumours." (PMID 25521701, 2014). "We have recently reported that concurrent targeting of BRCA2 and thymidylate synthase in A549 and Hela cells with antisense molecules sensitizes these human tumor cells to cisplatin and melphalan in a fashion consistent with complementary lethality." (PMID 24784564, 2014).
tumor (continued). "• M′′ - those with lower co-expression in normal vis-a-vis PDAC, or lower co-expression in BRCA1 tumours vis-a-vis BRCA2 tumours." (PMID 25521701, 2014). "Mutations in the DNA damage response (DDR) factors, breast cancer 1 (BRCA1) and BRCA2, sensitize tumor cells to poly(ADP-ribose) polymerase (PARP) inhibitors." (PMID 24252502, 2013). "We also assessed germline and somatic genomic imbalances in 15 patients (blood and tumor matched samples), 7 of which carried BRCA1/2 germline mutations (3 in BRCA1 and 4 in BRCA2), and 6 and 2 of which harbored BRCA1/2 wild type and BRCA1/2 UVs, respectively." (PMID 23469205, 2013). "Multiple studies have shown that aCGH classifiers can be built to distinguish BRCA1 and BRCA2 tumours from sporadic tumours and each other." (PMID 23383274, 2013). "The spectrum of tumours in families segregating BRCA1 and BRCA2 mutations includes pancreatic, prostate, colon and skin cancers." (PMID 24025454, 2013). "For example, Phase I and II clinical trials have shown that the PARP inhibitor olaparib (AZD2281) can elicit significant and sustained anti-tumour responses, especially in familial cancer patients with BRCA1 or BRCA2 mutant tumours [reviewed in]." (PMID 22933245, 2012). "Of the 110 TNBC patients included in this study and for whom germline status of BRCA1 and BRCA2 has been characterized (see earlier), 34 had adequate invasive tumor tissue for evaluation." (PMID 23116406, 2012). "BRCA2 tumours, in turn, demonstrate more ER positivity, while the rate of PR and HER2 receptor positivity is similar to that of sporadic tumours." (PMID 22312502, 2011). "For TAS106-induced down-regulation of BRCA2 and Rad51 to result in tumor radiosensitization, it needs to be maintained during the period of initial DSB repair after X-irradiation." (PMID 21798026, 2011). "Counting the number of tumor cells positive for Ki-67 against the total number of tumor cells reveals generally higher proliferation rates among triple-negative BRCA2 tumors compared with luminal BRCA2 tumors (χ2 test; P = 0.004)." (PMID 21958427, 2011). "BRCA2 functions as a tumor suppressor gene which stabilizes DNA structures at stalled replication forks." (PMID 20953429, 2011). "The distribution of grade has been found to vary between ER-positive and ER-negative tumours in both BRCA1 and BRCA2 mutation carriers (Mavaddat N, Antoniou AC, personal communication, manuscript in preparation)." (PMID 22053997, 2011). "Nevertheless, the differences in disease outcome with respect to ploidy in BRCA2 carriers are compelling and suggestive of divergent tumor-progression paths." (PMID 21958427, 2011). "This is a reasonable assumption since more than 90% of mutation carriers in our sample were recruited prior to 2007, when it was uncommon to use tumour pathology in selecting individuals for BRCA1 and BRCA2 mutation screening." (PMID 22053997, 2011). "As CK expression among TN tumours in BRCA2 carriers was similar to the distribution among TN tumours in breast cases unselected for FH and not tested for mutation (P > 0.05), we used data from these controls for BRCA2 carriers in our analyses." (PMID 20482762, 2010).
tumor (continued). "The biological and genetic profiles of the xenograft were compared with that of the patient's tumour using histology, immunohistochemistry (IHC), BRCA2 sequencing, comparative genomic hybridisation (CGH), and qRT–PCR." (PMID 20877358, 2010). "Our data indicate that amplification of the MYC locus and loss of the RB/INTS6 locus occurs in all mouse and human tumor groups, and that AURKA amplification occurs in mouse and human BRCA2-mutated tumors." (PMID 20735817, 2010). "Gains in the regions 1q32–q41, 8q22.1–24.3, and 20q12–q13, and loss in the region 8p23.3–p21.2 occur in both the primary and xenograft tumours and have also been found in primary BRCA2 tumours by different authors." (PMID 20877358, 2010). "The informativity of the two studied markers located at the BRCA2 locus, D13S260 and D13S1701, has allowed detecting the presence of the two alleles at the germline DNA level, whereas the primary tumour and the xenograft DNA showed loss of one allele." (PMID 20877358, 2010). "BRIT1 protein (also known as MCPH1) contains 3 BRCT domains which are conserved in BRCA1, BRCA2, and other important molecules involved in DNA damage signaling, DNA repair, and tumor suppression." (PMID 20107607, 2010). "There were many men with PrCa in these families; however, 20 were confirmed to be BRCA2 carriers, and 14 of them had tumours that were available for analysis by multiplex ligation-dependent probe amplification (MLPA)." (PMID 20736950, 2010). "Cohorts of male control (Brca2F/F), Brca2 heterozygous (Brca2F/+;PBCre4) and Brca2 mutant (Brca2F/F;PBCre4) animals were generated and analysed for tumour progression at 6 months, 10–14 months and 15–20 months of age." (PMID 20585617, 2010). "This study provides evidence that Brca2 can act as a tumour suppressor in the prostate, and the model we describe should prove useful in the development of new therapeutic approaches." (PMID 20585617, 2010). "Despite the genetic disparity, the similarities in behaviour between these sporadic tumours and BRCA1 and BRCA2 deficient tumours has been termed ‘BRCAness’." (PMID 24281034, 2010). "Principal common CNAs were the well known MYC-associated gain and RB1/INTS6-associated loss that occurred in all mouse and human tumor groups, and the AURKA-associated gain occurred in BRCA2-related tumors from both species." (PMID 20735817, 2010). "First, both BRCA1 and BRCA2 are tumour suppressor genes and most often involve wild-type loss of heterozygosity (wt-LOH) in mutation carriers' tumours, resulting in both parental copies of the gene being damaged in line with Knudson's two-hit model." (PMID 20637093, 2010). "In summary, our model suggests that BRCA2 acts as a tumour suppressor in the prostate and provides a pre-invasive model to test novel therapeutics." (PMID 20585617, 2010). "Classification of genomic profiles through cluster analysis revealed four distinct subgroups of which two displayed high prevalence of tumours having either BRCA1- or BRCA2 abnormalities." (PMID 19589159, 2009).
tumor (continued). "When stratified by BRCA mutation status, HIF-1α positivity was significantly correlated with BRCA1 (23/32, 72%) compared with BRCA2 (12/32, 38%) and BRCAX (20/49, 41%) associated tumours (P=0.008)." (PMID 19724277, 2009). "The results suggest that BRCA1- and BRCA2-related tumours develop largely through distinct genetic pathways in terms of the regions altered while also displaying distinct phenotypes." (PMID 19589159, 2009). "Although BRCA1- and BRCA2-related tumours develop through alterations affecting different regions in their genomes they showed similarities in their genomic architecture patterns with large segments of deletions being prominent." (PMID 19589159, 2009). "Tumours within the BRCA1- and BRCA2-related genomic subgroups were found to acquire genomic alterations affecting distinct regions of their genomes while also displaying distinct tumour phenotypes." (PMID 19589159, 2009). "In contrast to MLH1, BRCA1 and BRCA2 expression demonstrated greater variability between paired primary and recurrent neoplasms." (PMID 19602291, 2009). "BRCA1, located at 17q21, and BRCA2, located at 13q12-q13 both encode tumor suppressors involved in repairing double-stranded DNA breaks and maintaining genomic stability Germline BRCA1 or BRCA2 mutations are present in 10% to 15% of all EOCs." (PMID 18208621, 2008). "Tumours from familial non-BRCA1/BRCA2 patients were similar to sporadic ones, although they were of lower stage and CK-14 was expressed more often than among sporadic tumours." (PMID 18275599, 2008). "By contrast, the BRCA2 tumours arise with various status for the oestrogen, progesterone and HER2 receptor." (PMID 18627636, 2008). "PALB2 encodes a protein that binds to BRCA2 and this interaction is crucial for certain BRCA2 DNA damage response and tumor suppression functions." (PMID 18501021, 2008). "We also detected CK-14-positive staining among 27% of BRCA2 associated tumours and 21% of the non-BRCA1/BRCA2 associated tumours." (PMID 18275599, 2008). "BRCA2-associated tumours were also significantly more often negative for ER, PR and HER2, and detected at earlier age than sporadic tumours or non-BRCA1/BRCA2 tumours." (PMID 18275599, 2008). "In univariate analysis, CK-14 was significantly associated with tumours from BRCA1 (39%; P < 0.0005), BRCA2 (27%; P = 0.011), and non-BRCA1/BRCA2 (21%; P < 0.005) families, as compared with sporadic tumours (10%)." (PMID 18275599, 2008). "Concomitant losses of the BRCA1 region, which is located at the marker D17S855 together with the BRCA2 region were significantly related to the histological grade of the tumor." (PMID 17915011, 2007). "In contrast to this, c-Myc was found to be amplified in 23% (3/13) of BRCA1 and 67% (4/6) BRCA2 tumours." (PMID 16595007, 2006). "BRCA2 tumours expressed cyclin D1 and D3, cyclin D kinase (CDK) 4 and the CDK inhibitors, p16, p21, and p27, which were all downregulated in BRCA1." (PMID 16595007, 2006). "BRCA1 and BRCA2 tumours have also recently been subjected to TMA analysis in which 37 biomarkers were used to define hormone receptor, cell cycle, apoptosis and basal cell status." (PMID 16595007, 2006). "Instead, it is possible that BRCA2 plays a tumorigenic role primarily late in the development of a neoplasm." (PMID 16417627, 2006). "This is the first association study reporting results on EMSY, a gene of importance through its interaction with BRCA2 and its amplification status in tumours." (PMID 16029503, 2005). "Of course, a potential confounding issue was the differential distribution of ER between the BRCA1 and BRCA2 tumours." (PMID 15714204, 2005). "It is interesting that the BRCA1 and BRCA2 tumours appear to be opposites with respect to their characteristics in the age groups of younger and older patients." (PMID 15987451, 2005).
tumor (continued). "In the 30 BRCA2 cases, average age was 40.3 years, 62% of patients were premenopausal, 7% had T3-T4 tumours, 67% were node positive, 69% had G3 and 29% oestrogen receptor negative tumours." (PMID 15996267, 2005). "In BRCA2 families, tumours of patients diagnosed at less than 50 years of age differed significantly from those of the older patients for ER-negativity (20.6% vs 52.6%, respectively, P = 0.017) and PR-receptor negativity (35.3% vs 80.0%, P = 0.001)." (PMID 15987451, 2005). "Complementary DNA (cDNA) expression analysis has suggested distinct expression profiles for BRCA2 tumours as well." (PMID 15642173, 2005). "As in the initial tumor series, BRCA2, DNMT3B and CCNE1 mRNA levels were significantly higher in patients who relapsed than in those who did not relapse." (PMID 15606925, 2004). "This appears to be of specific interest taking into account that these tumours appear to displace a peculiar gene expression profile as compared to BRCA2 and sporadic tumours." (PMID 12698198, 2003). "It is well known that BRCA1 and BRCA2 reach their maximal levels in late G1 and S phases in normal and tumour-derived breast epithelial cells." (PMID 12838319, 2003). "Selective LOH at BRCA2 occurred in 7% of the tumours, whereas selective LOH at RBI was observed in another 7%." (PMID 8932343, 1996). "Deletion mapping of these 20 tumours indicated two separate commonly deleted regions: one was located in the region including RB and the other was located in the region including the BRCA2 locus." (PMID 7640222, 1995). "For example, BRCA1 exon 11‐deficient tumours and BRCA2 mutants lacking the BRC6–8 repeats have been associated with PARPi resistance." (PMID 41537447, 2026). "Therefore, DREAM- and RB-mediated transcriptional control of BRCA1 and BRCA2 constitutes a critical component of the regulatory network governing DNA repair, cell survival, and tumor suppression." (PMID 40841483, 2026). "It induces DNA damage and SL in BRCA1/BRCA2‐mutant tumour cells." (PMID 41537447, 2026). "Additionally, our findings provide mechanistic insight that supports and extends a previously proposed rationale for why BRCA1 and BRCA2 typically fail to exert tumor-suppressive functions in most cell types." (PMID 40841483, 2026). "BRCA2 functions as a tumor suppressor because of its role in error free DNA repair by HR1." (PMID 41542399, 2026). "BRCA1 and BRCA2 are core tumour suppressor genes in the HRR pathway." (PMID 41537447, 2026). "The only patient with confirmed PR by RECIST had a tumor with somatic BRCA2 loss and had not received PARPi." (PMID 41231232, 2025). "In this exploratory analysis, we evaluated associations of tumor-infiltrating lymphocytes (TILs), T-cell‒inflamed gene expression profile (TcellinfGEP), BRCA1/BRCA2 mutation (BRCAm) status, homologous recombination deficiency (HRD) status, and tumor mutational burden (TMB) with clinical outcomes." (PMID 41038856, 2025). "Our findings suggest that the absence of BRCA1 or BRCA2, and thus deficient repair, leads to gene mutation and tumor initiation through the emergence of transcriptionally associated DSBs in genes categorized as tumor suppressors and proto-oncogenes." (PMID 41350536, 2025). "Another tumor (TCGA-CI-6624) had a contribution of 28% of SBS8, with two somatic missense variants in BRCA2 of unknown pathogenic effect, as well as one each in RAD51AP2 and BRCC3." (PMID 41194282, 2025). "We also examined whether the low HRD scores obtained in BRCA2- and BRCA1-mutated cases in our study are attributed to suboptimal tumor cell content in the corresponding tissue samples." (PMID 41465280, 2025). "The breast cancer susceptibility genes (BRCA) are tumor suppressor genes including BRCA1 and BRCA2." (PMID 40182045, 2025).